ENG (endoglin)
Diseases named in the same sentence as ENG in open-access papers (continued):
Sharing a sentence is not in itself a finding about the gene and the disease.
hereditary hemorrhagic telangiectasia (continued). "Presently, ENG (endoglin) on chromosome 9q33-q34 and ACVRL1 (activin-receptor-like kinase) on chromosome 12q13 are the two genes primarily implicated in the development of Hereditary Hemorrhagic Telangiectasia (HHT)." (PMID 19508727, 2009). "More rarely, mutations in activin receptor like kinase type 1 (ACVRL1 or ALK1) or endoglin genes, also coding for members of the TGF-ß signaling family, have been identified in patients with PAH, predominantly with coexistent hereditary hemorrhagic telangiectasia." (PMID 23829793, 2013). "The observation of the development of PAH in patients displaying hereditary hemorrhagic telangiectasia (HHT), an autosomal dominant vascular dysplasia, allowed us to identify two other PAH predisposing genes: ACVRL1 (Activin A receptor type II-like kinase 1) and ENG (endoglin) genes." (PMID 23829793, 2013). "Dominant causes included 22q deletion syndrome, DYNC1H1, SCN3A, and hereditary hemorrhagic telangiectasia (HHT) genes, ACVRL1 and ENG." (PMID 41670011, 2026). "Second, early analysis of human families where a vascular disease called Hereditary Hemorrhagic Telangiectasia (HHT) segregated showed clear linkage to the BMP pathway genes ALK1 (HHT2) and endoglin (ENG, HHT1)." (PMID 35044529, 2022). "Follow-up genetic testing for hereditary hemorrhagic telangiectasia (HHT) by ACVRL1 and ENG gene sequencing and duplication/deletion analysis was negative." (PMID 25379312, 2014). "These entities are often sporadic but are found in association with variants of the RASA1 and EPHB4 genes (capillary malformation–arteriovenous malformation, CMAVM; OMIM #608354) or ACVRL1, ENG, and SMAD4 genes (hereditary hemorrhagic telangiectasia, HHT; OMIM #187300)." (PMID 40259928, 2025). "Another example is hereditary Hemorrhagic Telangiectasia (HHT), a class of genetic disease resulting from heterozygous mutations of ALK1 or endoglin (ENG), a non-kinase accessory protein for ALK1." (PMID 31331111, 2019). "However, unlike hereditary hemorrhagic telangiectasia (HHT) type 1 bAVMs, in which endoglin expression is reduced, levels of endoglin were found to be normal with increased numbers of endoglin-positive endothelial and adventitial cells." (PMID 41300153, 2025). "Mice lacking ALK1, its co-receptor endoglin, or the common effector SMAD4, are involved in the pathogenesis of hereditary hemorrhagic telangiectasia (HHT), characterized by the presence of telangiectasias and arteriovenous malformations." (PMID 35954181, 2022).
preeclampsia (145 papers, 2008 to 2026). Preeclampsia is a hypertensive disorder of pregnancy that is characterized by new-onset hypertension with proteinuria presenting after 20 weeks of gestation, and depending on mild or severe forms may initially present with severe headache, visual disturbances, and hyperreflexia. "Endoglin, a critical biomarker associated with preeclampsia risk, was targeted, and the biosensor demonstrated a linear detection range from 10 to 50 ng/mL, encompassing the clinically relevant concentrations of endoglin." (PMID 39727876, 2024). "Clinical studies have demonstrated that endoglin levels exceeding 20 ng/mL are associated with a significantly increased risk of preeclampsia." (PMID 39727876, 2024). "The most promising markers for earlier diagnosis of preeclampsia is soluble endoglin (sEng), pregnancy-associated plasma protein-A (PAPP-A), soluble fms-like tyrosine kinase 1 (sFlt-1), and placental growth factor (PlGF)." (PMID 35089126, 2022). "An increase in soluble endoglin is a hallmark of preeclampsia and is responsible for endothelial damage by trapping soluble TGF‐β molecules." (PMID 35582873, 2022). "An increase in the concentrations of maternally circulating endoglin and sFlt1, and a subsequent decrease in placental growth factor (PlGF) signaling were identified as the major causal factors for the development of preeclampsia." (PMID 34992598, 2021). "The binding of aPL by ApoER2-stimulated PP2A, which reduced proliferation and trophoblastic migration associated with the development of preeclampsia for upregulation in hypoxia-inducible factor 1 and soluble endoglin." (PMID 34925061, 2021). "The concentrations of complement proteins (adipsin, C3a, and C5a) and soluble endoglin (sENG) in the plasma were measured in this study, and their value as early-pregnancy predictors and potential diagnostic marker of preeclampsia was assessed, respectively." (PMID 34671343, 2021). "Thereafter, large amounts of serum factors (e.g., soluble fms-like tyrosine kinase 1 and soluble endoglin) are released into the blood from the hypoplastic placenta, and preeclampsia characterized by multiorgan disorder caused by vascular disorders develops." (PMID 33806480, 2021). "Endoglin and its soluble form, sENG, are angiogenesis-modulatory factors that are thought to have a role in the development of preeclampsia, and associations have been found at the gene, mRNA, and protein level." (PMID 29580923, 2018). "In ECs, membrane endoglin is a proteolytic substrate of MMP14 resulting in the release of soluble endoglin, which is associated with systemic hypertension during pregnancy and contributes to the pathogenesis of preeclampsia." (PMID 26850053, 2016). "Preeclampsia is associated with the placental release of soluble fms-like tyrosine kinase 1 (sFlt-1) and soluble endoglin (sENG)." (PMID 27207105, 2016). "Preeclampsia is associated with the placental release of soluble fms-like tyrosine kinase 1 (sFlt-1) and soluble endoglin (sENG) into the maternal circulation leading to hypertension, proteinuria and multi-system organ injury." (PMID 27207105, 2016). "At variance with the pro-angiogenic role of membrane-bound endoglin, soluble endoglin displays an anti-angiogenic activity, which has been postulated as a pathogenic contributor in preeclampsia." (PMID 26850053, 2016). "Recent studies demonstrated that serum endoglin concentrations were significantly increased in patients with preeclampsia and positively associated with preeclampsia severity." (PMID 27736929, 2016). "Taken together, these results suggested that placental LXRα and endoglin levels were upregulated in patients with preeclampsia and closely associated with preeclampsia disease activity." (PMID 27736929, 2016). "An imbalance of angiogenic and antiangiogenic placental factors such as endoglin and soluble fms-like tyrosine kinase 1 has been implicated in the pathophysiology of preeclampsia." (PMID 26413360, 2015).
preeclampsia (continued). "Our results further suggest that the pathway’s involvement in preeclampsia differs in whites and blacks, with ENG and TGFBR2 being associated in whites and TGFβ1, TGFβR1, and TGFβR2 being associated in blacks." (PMID 23548068, 2013). "This study investigated if endoglin (ENG) pathway genetic variation was also associated with the development of preeclampsia." (PMID 23548068, 2013). "Our study proposed to test the role of ENG in preeclampsia by assessing if ENG pathway genetic variations are associated with preeclampsia." (PMID 23548068, 2013). "ENG tSNP rs10121110 is also located between exons coding for ENG’s extracellular domain, as is rs11792480, the other tSNP associated with preeclampsia in whites." (PMID 23548068, 2013). "Given soluble endoglin has been implicated in severe preeclampsia, we only examined placentas obtained from cases of very severe disease." (PMID 22768148, 2012). "Severe preeclampsia is associated with increased neutrophil activation and elevated serum soluble endoglin (sEng) and soluble Flt-1 (sFlt-1) in the maternal circulation." (PMID 22398973, 2012). "Soluble endoglin was strongly correlated with sFlt1 and PlGF levels, suggesting common pathogenic pathways leading to preeclampsia." (PMID 23110221, 2012). "Differences in circulating concentrations of antiangiogenic factors sFlt1 and soluble endoglin (sEng) and the pro-angiogenic growth factor PlGF are reported to precede the onset of preeclampsia weeks to months in low-risk pregnant women." (PMID 20948996, 2010). "A possible physiological pathway involves abnormal increases in soluble fms-like tyrosine kinase-1 (sFlt-1) and soluble endoglin (sEng), accompanied by a decrease in placental growth factor (PlGF), which have been implicated in the pathogenesis of preeclampsia." (PMID 41115997, 2026). "Moreover, preeclampsia is likely polygenic, influenced by multiple susceptibility genes such as prothrombin, angiotensin converting enzyme, endoglin and apolipoprotein A134." (PMID 41287642, 2025). "Indeed, these authors reported that the administration of a CSE inhibitor increased the release of plasma antiangiogenic factors (sFLT1 and endoglin), thereby increasing the risk of preeclampsia." (PMID 38276547, 2024). "These experiments raise the possibility that deregulation of the ENG-LTR10A element may be associated with elevated levels of ENG in preeclampsia." (PMID 37012406, 2023). "The soluble form of endoglin, an antiangiogenic factor secreted by the placenta that impairs monocyte migration and differentiation into macrophages, increases in maternal plasma with preeclampsia associated with maternal vascular lesions." (PMID 35471950, 2022). "In addition, preeclampsia is associated with an increase in placental anti-angiogenic agents (sFlt1 or sVEGFR-1) and endoglin because the administration of these agents to pregnant mice causes preeclampsia." (PMID 36093083, 2022). "Endoglin (ENG) is yet another hypoxia-induced protein implicated in preeclampsia." (PMID 34831277, 2021). "Interestingly, high plasma levels of a soluble form of endoglin are found in patients with preeclampsia, a leading cause of maternal and prenatal morbidity associated with systemic hypertension, chronic inflammation and thrombocytopenia." (PMID 29080903, 2018). "•Genetic variation in endoglin pathway genes is associated with preeclampsia." (PMID 29580923, 2018). "Because soluble endoglin has been postulated to have a pathogenic role in preeclampsia and retains its capacity to bind integrins (; this work), it will be interesting to explore whether soluble endoglin has an impact on platelet function in this disorder." (PMID 29080903, 2018). "Preeclampsia is a disease of pregnancy associated with placental oxidative stress, inflammation and elevated release of anti-angiogenic factors sFlt-1 and soluble endoglin." (PMID 28500309, 2017).
preeclampsia (continued). "Elevated LXRα and endoglin levels may be associated with preeclampsia pathogenesis and development and could be used as potential predictors for this disorder." (PMID 27736929, 2016). "Therefore, our data indicated that increased endoglin was associated with preeclampsia development and progression." (PMID 27736929, 2016). "Recent observations suggested that abnormal liver X receptor alpha (LXRα) and endoglin expression, associated with lipid metabolic disturbances and trophoblast proliferation, might play important roles in preeclampsia development." (PMID 27736929, 2016). "Although we do not know the functional consequences of these associations, several explanations could account for the association between ENG (rs10121110 and rs11792480) and TGFβR2 (rs6550005) genetic variation and preeclampsia in white women." (PMID 23548068, 2013). "Soluble endoglin cooperates with sFlt1 to induce endothelial dysfunction in human umbilical vein endothelial cells (HUVECs), and simultaneous administration of both causes a severe preeclampsia-like illness in rats." (PMID 22929622, 2012). "Soluble endoglin is an anti-angiogenic protein released from placenta and thought to play a central role in causing the endothelial dysfunction and maternal organ injury seen in severe preeclampsia." (PMID 22768148, 2012). "In particular, it is unknown whether the concentration of soluble endoglin, a key angiogenesis inhibitor implicated in the pathogenesis of preeclampsia cardiovascular disease, hypertension and endothelial dysfunction, is correlated with GFR." (PMID 21886815, 2011). "From the molecular point of view, preeclampsia is associated with the upregulation of circulating levels of anti-angiogenic factors soluble Flt-1 (sFlt-1) and soluble endoglin that might account for maternal vascular dysfunction and oxidative stress described in preeclampsia." (PMID 34196872, 2021). "We previously reported that autophagy in EVTs was inhibited by soluble endoglin in preeclamptic placentas as one of the causes for the pathophysiology of preeclampsia, and the overexpression of HIF1α was significantly higher in placental biopsies from preeclampsia than in normal placentas." (PMID 24098539, 2013). "It has been shown in animals and in humans that an excess of circulating anti-angiogenic factors such as sFlt1 and soluble endoglin may play a pathogenic role in the development of maternal proteinuria and elevated blood pressure, the characteristic clinical signs of preeclampsia." (PMID 22097923, 2012). "Clinically, elevated sEng levels are observed in both early and late preeclampsia; high endoglin blocks the action of TGF-β, facilitating CD4+ differentiation toward Th17." (PMID 41156157, 2025). "Soluble endoglin (sEng), another antiangiogenic protein that has been extensively studied in preeclampsia, is an endogenous inhibitor of TGF-β1 (transforming growth factor β1)." (PMID 41303027, 2025). "In particular, the expression of ATF3 is significantly decreased in preterm placentas, and ATF3 is the regulator of soluble fms-like tyrosine kinase 1 (sFlt-1) and soluble Endoglin (sEng), which are important markers of premature delivery and preeclampsia." (PMID 40233080, 2025). "Studies have shown that patients with preeclampsia are characterized by elevated sFLT1, soluble endoglin, and endothelin-1 levels that are induced by elevated placental HIF-1 levels." (PMID 38678187, 2024). "With a limit of detection (LOD) of 5.4 ng/mL, the biosensor effectively captures early changes in endoglin levels that are indicative of preeclampsia onset." (PMID 39727876, 2024). "Here, we present the development of a hybrid biosensor platform for the ultrasensitive detection of endoglin, aimed at enabling the early diagnosis of preeclampsia." (PMID 39727876, 2024). "Given the clinical importance of endoglin as a biomarker, there is an urgent need for a rapid, cost-effective biosensor that can facilitate early diagnosis of preeclampsia." (PMID 39727876, 2024).
preeclampsia (continued). "Encouragingly, essential differentially expressed genes implicated in Preeclampsia, such as FLT-1, Endoglin, and ADAMTS, were predicted targets of the differentially expressed microRNAs in our study." (PMID 38628314, 2024). "A substantial proportion of the overexpression of the FLT1, LEP, and ENG in preeclampsia was mediated by placental cell composition." (PMID 36914823, 2023). "Preeclampsia is characterized by high soluble endoglin (sEng) concentration in plasma and coincides with intrahepatic cholestasis during pregnancy (ICP), which threatens the fetus with the toxicity of cumulating bile acids (BA)." (PMID 36778021, 2023). "Cellular composition mediated a substantial proportion of the association between preeclampsia and FLT1 (37.8%, 95% CI [27.5%, 48.8%]), LEP (34.5%, 95% CI [26.0%, 44.9%]), and ENG (34.5%, 95% CI [25.0%, 45.3%]) overexpression." (PMID 36914823, 2023). "Two major antiangiogenic factors associated with preeclampsia are soluble fms-like tyrosine kinase-1 and soluble endoglin, which are both increased in preeclampsia." (PMID 37614711, 2023). "Recently, another biomarkers, like the soluble fms-like tyrosine kinase 1 (sFlt-1), endoglin, PlGF, neurokinin-B have been used to try to predict the preeclampsia's onset and/or preeclampsia's complications." (PMID 36337683, 2022). "Research on the pathogenesis of preeclampsia has unveiled substantial pivotal molecule factors, like soluble endoglin (sEng), soluble FMS-like tyrosine kinase-1 (sFlt-1), placental growth factor (PlGF), and vascular endothelial growth factor (VEGF)." (PMID 35528613, 2022). "Among the other known biomarkers of preeclampsia—sFLT-1, pregnancy-associated plasma protein A (PAPP-A), placental growth factor (PIGF), and endoglin (ENG)—PIGF and PAPP-A were indeed significantly different between normotensive and preeclamptic women." (PMID 36569558, 2022). "Serous exosomes were also reported to induce preeclampsia by delivering sFlt-1 and soluble endoglin (sEng) or other constituents of the complex." (PMID 36160709, 2022). "These antiangiogenic factors, including tyrosine kinase-1 and soluble endoglin, can lead to endothelial damage and the clinical features that define preeclampsia." (PMID 35267975, 2022). "Vitamin D alters angiogenic factors (vascular endothelial growth factor or VEGF, placental growth factor or PIGF) and antiangiogenic factors (soluble VEGF receptor-1 or sFlt-1, soluble endoglin sENG) via placental gene expression in preeclampsia." (PMID 34991614, 2022). "The detergent-insoluble proteins included more endoglin, whose soluble forms are upregulated in the preeclampsia serum, and less vimentin, which is a structural protein of the aggresome." (PMID 33670947, 2021). "Another limitation is the absence of levels of proinflammatory cytokines, including sFlt-1 and soluble endoglin, that have been previously identified with preeclampsia." (PMID 34984051, 2021). "Administration of sFlt1 and soluble endoglin leads to the development of preeclampsia in pregnant rats." (PMID 33670947, 2021). "Among them, the increase in antiangiogenic factors, soluble Fms-like tyrosine kinase-1 (sFlt1) and soluble endoglin, in the maternal circulation are the most frequently investigated both in preeclampsia clinically and in basic science." (PMID 33670947, 2021). "Antiangiogenic factors, such as soluble fms-like tyrosine kinase 1 (sFlt1) and soluble endoglin (sEng), are long known to be involved in preeclampsia." (PMID 34195300, 2021). "When pregnant rats are given sFlt1 and soluble endoglin at mid gestation, it has been shown to mimic key features of severe preeclampsia with HELLP." (PMID 34827172, 2021). "Another antiangiogenic factor secreted during Preeclampsia is soluble Endoglin (sEng), which reduces the proangiogenic and vasodilator effects of Endoglin." (PMID 34867473, 2021).